NPY (neuropeptide Y)
Description:
[Neuropeptide Y]: Ligand for neuropeptide Y receptor type 1 (NPY1R) and neuropeptide Y receptor type 2 (NPY2R). Receptor binding induces adenylate cyclase-inhibiting G protein-coupled receptor signaling, resulting in inhibition of cAMP production. Receptor activation by NPY also leads to an increase of intracellular Ca(2+) levels. Is involved in the regulation of eating behaviour, acting as a stimulator of food intake (By similarity). Involved in the regulation of colonic antisecretory tone, and colonic contractility (By similarity).
Synonyms: PYY4
Tractability: Antibody: its Gene Ontology location is reachable by antibodies, with high confidence; UniProt places it where antibodies can reach, with medium confidence; UniProt predicts a signal peptide or a membrane-spanning region.
Gene: Protein-coding gene on chromosome 7 (24,284,188 to 24,291,862, forward strand). Ensembl gene ENSG00000122585.
Subcellular location: Secreted; Cytoplasmic vesicle, secretory vesicle, neuronal dense core vesicle
Subcellular location (Human Protein Atlas): Golgi apparatus; Predicted to be secreted
Pathways (Reactome):
Signal Transduction: G alpha (i) signalling events; Peptide ligand-binding receptors
Gene expression (Transcription): FOXO-mediated transcription of oxidative stress, metabolic and neuronal genes
Gene Ontology:
Molecular function: neuropeptide activity; protein binding; calcium channel regulator activity; G protein-coupled receptor activity; neuropeptide hormone activity; neuropeptide Y receptor binding; signaling receptor binding; G protein-coupled receptor binding; hormone activity
Biological process: adenylate cyclase-inhibiting G protein-coupled receptor signaling pathway; central nervous system neuron development; cerebral cortex development; G protein-coupled receptor signaling pathway; neuron projection development; positive regulation of cytosolic calcium ion concentration; adult feeding behavior; chemical synaptic transmission; feeding behavior; G protein-coupled receptor signaling pathway, coupled to cyclic nucleotide second messenger; intestinal epithelial cell differentiation; neuropeptide signaling pathway; positive regulation of appetite; positive regulation of eating behavior; developmental growth; drinking behavior; monocyte activation; negative regulation of acute inflammatory response to antigenic stimulus; negative regulation of blood pressure; positive regulation of cell population proliferation; positive regulation of cell-substrate adhesion; positive regulation of dopamine metabolic process; positive regulation of ERK1 and ERK2 cascade; regulation of nerve growth factor production; regulation of nitric oxide biosynthetic process; and 4 more
Cellular component: extracellular region; Golgi apparatus; neuronal dense core vesicle; cytoplasm; GABA-ergic synapse; perikaryon; perinuclear region of cytoplasm; terminal bouton
Genetic constraint (gnomAD): Loss-of-function variants: 9 observed, 11.03 expected, observed/expected ratio (o/e) 0.82, 90% interval 0.49 to 1.42. The upper end of that interval is the gene's LOEUF score, 1.42, which puts it in group 5 of 6, group 1 being the genes least tolerant of losing a copy. Missense variants: 105 observed, 124.24 expected, observed/expected ratio (o/e) 0.85, 90% interval 0.72 to 0.99. Synonymous variants: 47 observed, 56.63 expected, observed/expected ratio (o/e) 0.83, 90% interval 0.66 to 1.06.
Homologues: Orthologues: chimpanzee NPY (99% identical), guinea pig NPY (98% identical), rabbit NPY (98% identical), rat Npy (94% identical), dog NPY (93% identical), macaque NPY (93% identical), mouse Npy (93% identical), pig NPY (93% identical), tropical clawed frog npy (75% identical), zebrafish npy (66% identical). Paralogues in human: PYY (49% identical), PPY (36% identical).
Diseases named in the same sentence as NPY in open-access papers:
NPY is named in the same sentence as 401 diseases in open-access papers, as found by Europe PMC text mining. Sharing a sentence is not in itself a finding about the gene and the disease. The quoted sentences say what the papers report.
Obesity (349 papers, 2007 to 2026). Accumulation of substantial excess body fat. "Specifically, relatively higher levels of neuropeptide Y and orexin increase obesity risk, while elevated oxytocin levels reduce this risk." (PMID 41823115, 2026). "Among them, β-EP and NPY can stimulate appetite and participate in energy metabolism, probably leading to obesity, which is considered to increase the risk of OSAS." (PMID 40989139, 2025). "It was also investigating the expressions of obesity-related neuropeptide Y (NPY) and fat mass and obesity-associated gene (FTO) in the arcuate (ARN), ventromedial (VMN), and dorsomedial nuclei (DMN)." (PMID 40636869, 2025). "This process involves the use of recombinant adeno-associated viruses to increase neuropeptide Y levels in the paraventricular nucleus, resulting in hyperphagia and obesity in the affected rats." (PMID 40636308, 2025). "It has previously been suggested that obesity is not caused by hyperphagia, but that the lipogenic effects of NPY play a role in the obesity process." (PMID 40636869, 2025). "Abnormal DNA methylations of key metabolic-related genes, such as Leptin, adiponectin, PGC1α, IGF-2, appetite-related genes-(POMC, NPY), are frequently implicated in the development of obesity and insulin resistance." (PMID 40702315, 2025). "Maternal caloric restriction during pregnancy blunts the leptin neonatal surge, which impairs axon development from ARC POMC and AGRP/NPY neurons and leads to adulthood outcomes linked to vulnerability to obesity." (PMID 40474775, 2025). "The Y2R is in the centre of NPY-associated anti-obesity research and, until recently, a central stimulation would have been assumed to reduce weight and be beneficial, while a blockage would have been assumed to increase body weight." (PMID 38542814, 2024). "Nevertheless, in another study, Y1 receptor-deficient mice unexpectedly exhibited moderate obesity and modest hyperinsulinemia, which can suggest that the Y1-R deficiency is compensated by other receptors responsible for NPY signaling, e.g., Y5-R." (PMID 38542187, 2024). "The increased NPY levels in obesity will predispose to higher stimulation of feeding and lower energy expenditure by decreasing thermogenesis, WAT browning, WAT lipolysis rate, and hepatic β-oxidation while enhancing adipogenesis." (PMID 36830982, 2023). "DNA methylation can alter the expression of obesity-associated genes, such as neuropeptide Y (NPY), peroxisome proliferator-activated receptor gamma (PPARγ), fatty acid binding protein 4 (FABP4), and sterol regulatory element-binding protein-1 (SREBP-1)." (PMID 37627544, 2023). "In contrast, Ghrelin, referred to as a hunger hormone that increases food intake, and the neuropeptide Y (NPY) increases the risk of developing obesity." (PMID 37712012, 2023). "As an important peptide in the ANS, NPY signaling dysregulation is associated with energy balance perturbances and, therefore, with obesity." (PMID 36830982, 2023). "Decreased histone acetylation of POMC and increased acetylation of NPY have been linked to obesity following exposure to a high-fat diet." (PMID 37899888, 2023). "Alterations in NPY conformation and levels are linked to adiposity and altered metabolic control, with circulating NPY being increased in patients with obesity." (PMID 36830982, 2023). "Accordingly, individuals with the L7P polymorphism have, in addition to higher plasma NPY levels, a higher risk of being overweight or developing obesity and increased serum triglycerides." (PMID 36830982, 2023). "It has been shown that moxonidine normalized neuropeptide Y levels in serum and decreased hyperlipidemia, as well as decreasing the obesity-related risk of mortality and morbidity due to CVD." (PMID 35454311, 2022). "Reduced acetylation of H3K9 at the PMOC and increased acetylation of the same residue at the NPY gene have been associated with high-fat diet-induced obesity." (PMID 35163268, 2022).
Obesity (continued). "NPY overexpression in the paraventricular nucleus causes obesity by increasing food intake, whereas NPY knockdown in the hypothalamus promotes energy expenditure." (PMID 36532520, 2022). "NPY is associated with various diseases, including CNS diseases, cardiovascular diseases, obesity, adipose tissue inflammation, autoimmunity, and atherosclerosis." (PMID 34344469, 2021). "It has been shown polymorphisms in the NPY gene is associated with clozapine-induced weight gain and contributes to the development of obesity." (PMID 33716966, 2021). "Dysfunctions of the NPY system have been implicated in diseases such as obesity, type II diabetes and metabolic syndrome." (PMID 34445453, 2021). "Clozapine also affects other hormones associated with obesity such as ghrelin and neuropeptide Y (NPY)." (PMID 33716966, 2021). "Leptin knockout can relieve leptin’s inhibition of NPY neurons and cause obesity and inhibit NPY neurons by chemogenetic tools which can improve food intake and blood glucose levels in diabetic mice." (PMID 34307371, 2021). "Obesogenic diets alter the hypothalamic NPY expression, and elevated levels of NPY gene expression are found in several models of animal obesity such as diet-induced obesity (DIO), leptin deficient ob/ob mice and Zucker fatty fa/fa rats." (PMID 34445453, 2021). "On the other hand, NPY is an orexigenic neuropeptide associated with obesity, which is related to appetite regulation and development obesity." (PMID 32982666, 2020). "Neuropeptide Y is a key peptide affecting adiposity and has been related to obesity risk such as food intake and cardiovascular regulation." (PMID 33415147, 2020). "It has been reported that exposure to HFD-induced obesity can cause dysregulation of the expression of NPY and AgRP in the hypothalamus." (PMID 32585823, 2020). "Another study on HFD female DBA/2J mice proposed that obesity-linked hyperleptinemia, slowly prompted central leptin resistance, amplified hypothalamic neuropeptide Y transmission and eventually led to hypothalamic hypogonadism." (PMID 32082253, 2019). "The obesity-related changes in hormone levels, in particular leptin, adiponectin, ghrelin, neuropeptide Y and agouti-related protein, are associated with reproductive dysfunction at both the hypothalamic-pituitary and the ovarian levels." (PMID 29743077, 2018). "Obesity is also associated with ghrelin resistance in NPY/AgRP neurons in the ARC leading to reduced ghrelin- and fasting-induced appetite response." (PMID 29433631, 2018). "In humans, despite some conflictive reports, NPY gene variants have been significantly associated with weight changes from young adulthood to middle age and with risk of obesity." (PMID 28489853, 2017). "Overproduced as a central effector of leptin deficiency, NPY is associated with obesity, a typical symptom of T2DM and infertility, and eventually plays a major role on insulin action or secretion regulation in central nervous system (CNS)." (PMID 23671868, 2013). "We already reported that polymorphisms of the PON1 and NPY genes, which were associated with stroke and obesity, were related to DP among Korean stroke patients." (PMID 23043591, 2012). "Direct or indirect effects of NPY have been particularly implicated in obesity and metabolic syndromes." (PMID 22110543, 2012). "Many groups have studied the association of NPY polymorphisms with obesity and/or serum lipid levels." (PMID 22110543, 2012). "Sustained up-regulation of hypothalamic NPY is associated to a disruption of feeding patterns in rodent models of obesity such as Zucker rats, rats overexpressing NPY in the LH and, as reported in this study, rats overexpressing NPY in the ARC." (PMID 21799827, 2011). "The orexigenic neuropeptide Y (NPY) promotes food intake and causes obesity." (PMID 41373996, 2025). "The fact that EMF increases the expression of FTO and NPY in the hypothalamus may be evidence that it increases the risk of obesity in infant rats." (PMID 40636869, 2025).
Obesity (continued). "The effects of EMF on hypothalamic FTO and NPY expression in offspring rats after prenatal exposure may provide new evidence on the predisposition to obesity." (PMID 40636869, 2025). "NPY is a known appetite regulator and its mutation led to obesity and metabolic syndrome." (PMID 38469147, 2024). "In fact, administration of neuropeptide NPY causes increased food intake and obesity." (PMID 37375686, 2023). "NPY imbalance has been implicated in the development of metabolic diseases, including obesity, glucose tolerance, hypertension and atherosclerosis, but the functional significance and association with SZ remain unclear." (PMID 37958729, 2023). "Recent work has investigated whether changes in the function of ArcN NPY or POMC neurons in males with obesity underlie sensitization to the sympathoexcitatory effects of leptin and/or its metabolic partner, insulin." (PMID 36769012, 2023). "NPY (neuropeptide Y) is a sympathetic neurotransmitter belonging to the pancreatic polypeptide family, and a single-nucleotide polymorphism (SNP) associated with this gene is related to hypertension, obesity, diabetes, and cardiovascular disease." (PMID 35149954, 2022). "Targeted disruption of the Npy1r gene in limbic areas revealed that limbic NPY-Y1R system was involved in energy balance and emotional behavior, and selective inactivation of limbic Npy1r gene increased susceptibility to diet-induced obesity in male mice." (PMID 36267563, 2022). "In addition, recent studies have shown that obesity and stress are linked at the protein level, such as neuropeptide Y (NPY) or FK506-binding protein 51 (FKBP51)." (PMID 35565711, 2022). "The observed hyperphagia associated to an impaired habituation to high caloric food in NPY1rrfb mice might suggest that limbic NPY-Y1R system play a role in emotional eating disorder phenotype resembling human binge eating associated with obesity." (PMID 34445453, 2021). "Increased plasma LPN can transduce signals to obesity gene receptors in the hypothalamus to inhibit neuropeptide Y gene expression to cause food intake reduction and energy consumption and inhibit islet β-cells to secrete insulin, which feeds back to decrease LPN production." (PMID 33570444, 2021). "In addition to NPY itself, the mechanisms causing obesity also include the inflammatory response, in which macrophages play a role." (PMID 34344469, 2021). "Also among these genes is the neuropeptide Y receptor type 2 (Npy2r) which is a receptor for both NPY and peptide YY, variants of which are associated with obesity." (PMID 33424545, 2020). "Overexpression of NPY in mice has been reported to cause the obesity phenotype and insulin resistance, leading to a series of metabolic disorders, while the use of NPY antagonists has been found to reduce obesity and metabolic imbalances in fat tissue associated with aging." (PMID 32831640, 2020). "Zn deficiency and obesity can lead to leptin resistance which may increase NPY levels in the hypothalamus of rodents and men." (PMID 31827626, 2019). "In regards of its role in obesity, it has been shown that an increase in NPY is caused by high levels of glucocorticosteroids through directly activating type II glucocorticosteroids receptors and indirectly, by abolishing the negative feedback of CRF on NPY synthesis and release." (PMID 31191339, 2019). "NPY has been implicated in several human diseases involving fat deposition aberrations and obesity." (PMID 30348079, 2018). "Moreover, NPY raises the risk of obesity by upregulating NPY and NPY2R expression in the abdominal fat and its administration in rodents leads to lipogenic enzyme activation in adipose tissues, demonstrating its critical role in adipogenesis." (PMID 30105036, 2018). "However, increased NPY-signaling also drives the hyperphagia during obesity, which would contradict the association between obesity and anxiogenesis." (PMID 30210279, 2018).
Obesity (continued). "In this study, we elucidated whether pharmacological blockage of peripheral Y2-receptors with BIIE0246 would have beneficial effects on energy metabolism in a situation of excess energy and/or NPY, usually associated with obesity." (PMID 29674968, 2018). "Additionally, loss of NPY can combat obesity and diabetes through increased energy expenditure and lowered fat contents." (PMID 29190643, 2017). "NPY is overproduced in the hypothalamus of leptin deficient ob/ob mice; when depleted by genetic manipulation, ob/ob mice showed reduced food intake, increased energy expenditure and less obesity." (PMID 28489853, 2017). "NPY, which is mainly linked to the regulation of hunger and obesity, has recently been shown to contribute to osteoporosis- and osteoarthritis-related pain generation and perception in postmenopausal women, patients with knee osteoarthritis and in rat models of this disease." (PMID 28762133, 2017). "DMH NPY has been implicated in the hyperphagia and obesity of OLETF rats." (PMID 28575002, 2017). "Another central pathway involving increased neuropeptide Y (NPY) arising from leptin resistance during obesity is implicated in bone metabolism as mice with increased central NPY have concurrent obesity with bone loss and NPY deficiency in ob/ob mice leads to improved cortical bone mass." (PMID 27512386, 2016). "In support of leptin's modulatory role on these distinct neuronal populations are mouse models that show that the obesity syndrome classically studied in leptin-deficient mice (Lepob/ob), when crossed with NPY-null mice, reduces obesity as compared with Lepob/ob mice alone." (PMID 26819774, 2016). "Interestingly NPY deficient ob/ob mice became less obese due to the reduced food intake and had a attenuation of the obesity syndrome which suggests a role for NPY in leptin deficiency." (PMID 26945906, 2016). "Thus, the deletion of a CB1 receptor has been associated to hypophagia and leanness, whereas obesity has been associated to the overexpression of neuropeptide Y (which displays orexigen properties) and higher levels of 2-AG in the hypothalamus." (PMID 27806128, 2016). "An increase in NPY activity may be associated with cancer development via actions to promote weight gain, since overweight and obesity are related to an increased risk of cancer progression." (PMID 26153206, 2015). "Obesity in their mouse model was associated with increased circulating leptin levels, and an increase in the orexigenic factor NPY in the hypothalamus, an observation that is consistent with our microarray data suggesting a deregulation of food intake control in the brain." (PMID 25629159, 2015). "Indeed high fat-fed obesity-prone mice supplemented with the viscous fermentable fibre oat beta-glucan show suppression of arcuate NPY associated with the decreased voluntary food energy intake and increased satiety." (PMID 26447990, 2015). "Understanding the role of central vs. peripherally-derived NPY in whole-body energy balance could shed light on mechanisms underlying the pathogenesis of obesity." (PMID 24959194, 2014). "However, there was a trend to higher fasting insulin levels in KO→WT mice fed HFD suggesting that myeloid NPY deficiency increases insulin resistance with dietary obesity." (PMID 23472120, 2013). "To examine the significance of NPY production by macrophages/myeloid cells in obesity, we used BM chimeras to examine the hypothesis that loss of NPY from hematopoietic cells would increase adipose tissue inflammation." (PMID 23472120, 2013). "Thus, NPY and its receptors have been implicated in various biological functions and neuronal disorders, such as epilepsy, obesity, and anxiety." (PMID 24225225, 2013). "This suggests that increased NPY may have a diabetogenic effect in the context of obesity and supports the association of the L7P polymorphism with an earlier onset of diabetes in the obese human population." (PMID 23118773, 2012).